LGALS3 (galectin 3)
Diseases named in the same sentence as LGALS3 in open-access papers (continued):
Sharing a sentence is not in itself a finding about the gene and the disease.
cancer (continued). "Our previous studies showed that F3 binds to the galectin-3 CRD, induces galectin-3 conformational changes and inhibits galectin-3-mediated cancer cell adhesion and metastasis." (PMID 31413267, 2019). "The prognostic role of galectin-3 has been widely studied, but appears to be unclear and disparate between different cancer types." (PMID 31832021, 2019). "Galectin-3 is a member of the β-galactoside binding protein family that is involved in diverse functions inherent to cancer, such as metastasis, immune surveillance, inflammation, apoptosis, molecular trafficking, and mRNA splicing." (PMID 31105878, 2019). "Amongst them, due to its differential expression between cancer and normal tissues, galectin-3 was regarded as one important member of galectins family." (PMID 30410421, 2018). "The discrepancies among these studies highlighted the importance of evaluating the prognostic significance of galectin-3 in multiple human malignant neoplasms." (PMID 30410421, 2018). "Several molecules such as Thomsen-Friedenreich antigen (TF-Ag), galectin-3 (Gal-3) and different integrins are involved in adhesive interactions between cancer cells and endothelial cells." (PMID 30235349, 2018). "This is because galectin-3 promotes cancer and metastasis, and inhibition would hence have a great potential for therapeutic anticancer treatment." (PMID 29950926, 2018). "A promising target for directing glycopolymers to cancer-stricken tissue is galectin-3 (Gal-3)—the only representative of chimeric galectins in mammals." (PMID 30236114, 2018). "In the human gastric adenocarcinoma cells MKN-28 and SNU-638, galectin-3, a carbohydrate-recognition protein involved in cancer cell dissemination, increased PAR-1 expression and cell migration, using a zebrafish embryo in vivo model of cancer cell invasion." (PMID 30065215, 2018). "According to published data, the overexpression of galectin-3 occurs in cancers of tongue, thyroid, colon, liver, gastric, hepatocellular, and ovaries." (PMID 30267152, 2018). "In cancer, galectin-1 (Gal-1) and galectin-3 (Gal-3) are the most well-studied galectins and both have been shown to enhance cell proliferation, signaling, and migration." (PMID 30135430, 2018). "Another protein (which has been increasingly associated in the literature with the cancer resistance, due to its structure similarity to BCL-2 family members and its regulation by NF-κB) is galectin-3." (PMID 30267152, 2018). "The interaction between galectin-3 and cell adhesion molecules, such as integrin, cadherin and mucin 1, regulates the invasion and metastasis of cancer cells." (PMID 29414883, 2018). "A total of 33 eligible studies were enrolled to evaluate the role of elevated galectin-3 expression in multiple human malignant neoplasms by OS, within a random-effects model." (PMID 30410421, 2018). "In summary, it was the first time for us to shed light on the prognostic role of elevated galectin-3 expression in various cancers." (PMID 30410421, 2018). "This review focuses on the biological effects of galectin-1, galectin-3 and galectin-9 in various cancers and discusses anticancer therapies that target these molecules." (PMID 29389859, 2018). "The mechanism of action of MCP in inflammation, fibrosis, and cancer progression is that it works as a competitive inhibitor of extracellular galectin-3 (Gal-3)." (PMID 28900464, 2017). "Galectin-3 facilitates cancer growth and metastasis by several mechanisms, further highlighting the importance of the GnT-V and β-1,6-N-acetylglucosamine branched glycans in cancer." (PMID 28106780, 2017). "Galectin-3 overexpression attenuated the chemo-sensitivity of cancer cells, but enhanced the potential invasiveness." (PMID 28146425, 2017). "Changes in Galectin-3 expression and its subcellular and intercellular localization are commonly observed in cancer and precancerous conditions." (PMID 28390134, 2017).
cancer (continued). "The binding of galectin-3 to β-galactoside sugars on glycoproteins crosslinks between the glycoproteins and regulates diverse cellular functions in cancer cells." (PMID 28678156, 2017). "Auto-phosphorylation of FAK and activation of SRC is regulated by integrin clustering which dependents on Galectin-3 on the surface of cancer cells." (PMID 28701735, 2017). "But, Galectin-3 expression markedly reversed the effects of miR-128 as a cancer suppressor in CRC cells." (PMID 28146425, 2017). "Here we show that galectin-3 (gal-3), a glycan-binding protein secreted by cancer cells under hypoxic conditions, triggers sprouting angiogenesis, assisted by hypoxic changes in the glycosylation status of endothelial cells that enhance binding to gal-3." (PMID 28533486, 2017). "EGFR is associated in epithelial cells with the heavily glycosylated transmembrane mucin protein MUC1, a natural ligand of galectin-3 that is overexpressed in cancer." (PMID 28731466, 2017). "Altogether, Galectin-3 plays a certain role in cell motility, but its role in cancer cell proliferation and EMT needs to be further studied." (PMID 29254179, 2017). "Galectin-3 (Gal-3) is one such immune suppressive factor, which is highly expressed in malignant tumors." (PMID 28548942, 2017). "Asialofetuin binds to the lectins galectin-1 and galectin-3, which are located on the surface of cancer cells, and induces homotypic aggregation by serving as a cross-linking bridge between adjacent cells." (PMID 29185464, 2017). "We investigated the role of galectin-3 in chemo-sensitivity and invasion and identified miR-128 as a direct regulator of galectin-3 in cancer cells." (PMID 28146425, 2017). "Given the inverse correlation between miR-128 and Galectin-3 in cancer cells, and tissues combined with bioinformatics analysis, we posited that miR-128 potentially regulated Galectin-3 expression." (PMID 28146425, 2017). "Although many studies have been conducted on the mechanism responsible for Galectin-3 modulation of cancer progressions, its role in cancer metastasis of thyroid is still not well understood." (PMID 29254179, 2017). "A conceivable possibility in pathophysiological conditions, including cancers, is that part of extracellular galectin-3 is released passively from dying cells." (PMID 27242966, 2016). "Inhibition of this site, in particular in galectin-3, has been proposed or claimed as the mechanism behind the interesting anti-cancer and anti-inflammation effects of certain plant-derived polysaccharides (1, –, 6, 9, –, 16, 18, 19)." (PMID 27129206, 2016). "Using coculture of human fetal osteoblasts (hFOB) with cancer cells expressing galectin-3, these authors showed that galectin-3 secreted by cancer cells inhibited osteoblast differentiation, a Notch1-regulated process." (PMID 27242966, 2016). "Galectin-3 (gal3), a member of the β-galactoside-binding lectin family, is a multifunctional protein with various biological functions, including the cancer cell proliferation and invasion, and angiogenesis." (PMID 26872020, 2016). "Several other investigations subsequently also reported a role of galectin-3–TF interaction in mediating cancer cell adhesion to the endothelium in vitro and in mice." (PMID 27066458, 2016). "To strengthen the functional link of galectin-3 and hnRNPA2B1 in a cancer context we searched for oncogenes that were similarly affected by galectin-3 and hnRNPA2B1 knockdown." (PMID 27435226, 2016). "To date, the anti-cancer properties of heparins have been attributed to the attenuation of angiogenesis, galectin-3, heparanase and the inhibition of selectins (P- and E-selectin)." (PMID 27602496, 2016). "Galectin-3 is a member of the β-galactoside-binding lectin family, whose expression is often dysregulated in cancers." (PMID 27242966, 2016).
cancer (continued). "We show that sTn protects cancer cells against chemotherapeutic-induced cell death by decreasing the interaction of cell surface glycan receptors with galectin-3 and increasing its intracellular accumulation." (PMID 27835877, 2016). "Galectin-3 is also an important modifier of immune cell function, which will constitute now another layer of complexity in its roles in cancer progression, which will be dealt with in other reviews in this series." (PMID 27242966, 2016). "Exogenous galectin-3, through its ability to form lattices on the cell surface, restored FAK stabilization and cell motility in galectin-3 knockdown cancer cells." (PMID 27242966, 2016). "After cultivation in sphere forming culture media, the sphere size and the number of spheres were both smaller in galectin-3 depleted cells than in control cells Total number of cells to form cancer sphere were also lower than control cells." (PMID 27626163, 2016). "Increased levels of circulating galectin members, in particular galectin-3, are also commonly seen in cancer patients." (PMID 27066458, 2016). "Galectin-3 is overexpressed in several human cancers, including gastric, colon, and pancreatic cancers." (PMID 26934444, 2016). "In cancers of the thyroid, liver, stomach, and central nervous system the protein is upregulated, whereas in cancers of the breast, ovary, uterus and prostate galectin-3 is downregulated." (PMID 27435226, 2016). "It has been shown that galectin-3 (Gal3) is responsible for a myriad of biological processes in a wide variety of cancers." (PMID 27687248, 2016). "Expression and distribution of galectin-3 between the cell nucleus and the cytosol changes during cell differentiation and cancer development." (PMID 27435226, 2016). "It is well-documented that galectin-3 expression is altered in malignant tissues, and it has many functions in cancer progression, additionally the localization of this molecule is an important feature to understand its function, as already mentioned." (PMID 27242966, 2016). "Although it is known that galectin-3 regulates the activity of MAPK pathway in several cancer models, further studies are still necessary to elucidate the mechanistic details of the pro-survival activity of galectin-3." (PMID 27242966, 2016). "The extracellular Galectin-3 acts as an adhesion protein in cell-cell interactions and is involved in cancer progression and metastasis." (PMID 27754373, 2016). "Galectin-3 was expressed significantly more in malignant tumours (88.5 %) than in benign (35.4 %) (p = .000)." (PMID 26503236, 2015). "Galectin-3 plays an important role in invasion, modulating the adhesion between cancer cells and ECM, as well as potentiating angiogenesis." (PMID 26222311, 2015). "Such broad cancer- and metastasis-promoting actions of galectin-3 have prompted many laboratories over recent years to explore therapeutic strategies that target galectin-3." (PMID 26160844, 2015). "Increased cancer cell adhesion to vascular endothelium is one of the important metastasis-promoting effects of circulating galectin-3." (PMID 26160844, 2015). "It has also been reported that GCNT1-expressing cancers can escape the host immune response, especially from host natural killer cells that bind to galectin-3 on core 2-branching O-glycans." (PMID 26390303, 2015). "A higher level of circulating galectin-3 is also found in the bloodstream of cancer patients, particularly those with metastasis." (PMID 25669973, 2015). "Galectin-3-expressed on the surface of cancer cells acts as an adhesion molecule and promotes cancer cell-cell and cell-matrix interaction during cancer cell invasion and migration." (PMID 26160844, 2015). "Concentrations of circulating galectin-3, a metastasis promoter, are greatly increased in cancer patients." (PMID 26160844, 2015). "At galectin-3 concentrations comparable to serum levels of cancer patients, we detect the highest avidities." (PMID 26213980, 2015).
cancer (continued). "Circulating galectin-3 also promotes endothelial secretion of metastasis-promoting cytokines and cancer cell migration, proliferation and angiogenesis." (PMID 26160844, 2015). "The TF antigen seems to play a crucial role in the adhesion of cancer cells to the endothelium through the interaction with galectin-3, thereby promoting metastases." (PMID 26663951, 2015). "Exogenous galectin-3 induces the extracellular signal-regulated kinases (ERK1/2) phosphorylation in cancer cells, and the activation of ERK1/2 are associated with cancer cell proliferation and survival." (PMID 26273429, 2015). "Galectin-3 is present in human serum and plasma, and is used or is under consideration as marker for different conditions ranging from cancer to acute heart failure." (PMID 25869099, 2015). "We here establish that, in contrast to more mature B-lineage cancers, Galectin-3 detected in and on the ALL cells originates from stromal cells, which express it on their surface, secrete it as soluble protein and also in exosomes." (PMID 25869099, 2015). "Galectin-3, a cytoplasmic stain, has high sensitivity and specificity for malignant tumors, particularly PTC and FVPTC, though it is frequently expressed in FTC as well; FA, however, is negative." (PMID 26550511, 2015). "Galectin-3 is overexpressed by most types of cancer cells and is involved in cancer development, progression and metastasis." (PMID 26160844, 2015). "We note that serum Galectin-3 concentrations reported in cancer patients are up to 32 nM, in line with our data on Galectin-3 levels in bone marrow plasma from ALL patients." (PMID 25869099, 2015). "The effect of galectin-3 overexpression on the proliferation of Eca-109 cancer cells was determined by the CCK-8 assay." (PMID 25373317, 2015). "Of the MSC SASP factors, we found that galectin-3 was an important mediator of cancer-promoting activity." (PMID 26273429, 2015). "With cut off value of 7.5 % of follicular cells expressing Galectin-3, sensitivity is 89 %, and specificity is 65 % for carcinoma." (PMID 26503236, 2015). "In this research, we found that the induction of apoptosis in human HCC cancer cells by galectin-3 silence was mediated by caspase-dependent apoptosis pathways." (PMID 25260879, 2014). "In prostate tissues, the galectin-3 promoter is unmethylated, while it becomes strongly methylated in the early stages of prostate cancer, but less methylated in high-grade cancers." (PMID 25256425, 2014). "The expression levels of both galectin-3 and neogenin-1 were higher in cancer tissues than in normal tissues." (PMID 24930499, 2014). "The role of one member of this family in particular, namely galectin-3 (Gal-3), has been intensively investigated lately and it was shown that it is deeply involved in cancer metastasis and migration." (PMID 25161726, 2014). "Taken together, these results suggest that the expression of galectin-3 has an important influence on the development of malignant tumors." (PMID 25260879, 2014). "The expression of galectin-1 and galectin-3 mRNA in normal kidney and corresponding cancer tissue was analyzed using quantitative real time PCR." (PMID 24708743, 2014). "Galectin-3 has been found to be correlated to several cancers, including mesothelioma as well as cancer of breast, gastrointestinal system, and colon." (PMID 25260879, 2014). "Overall, TNC tumors expressed galectin-3 more frequently than the other cancer types (57.96% vs. 26.74%; P = 0.000)." (PMID 25254965, 2014). "pH-modified pectin as well as galactan-rich pectin (RG-I) are capable of interacting with galectin-3, thus inhibiting cell-cell interactions and cancer cell metastasis." (PMID 24115933, 2013). "Galectin-3, which is one of the most studied galectins, is an important regulator of a broad range of cancer cell activities and plays important roles in cancer cell growth, transformation, apotosis, angiogenesis, adhesion, invasion, and metastasis." (PMID 24339976, 2013).
cancer (continued). "Of note, when compared to PSA concentration, galectin-3 more consistently distinguishes metastatic PCa patients from the cancer-free controls." (PMID 23625538, 2013). "The levels of galectin-3 in the sera of the 8 metastatic PCa patients were all higher than any of those in the non-cancer control group." (PMID 23625538, 2013). "In particular, galectin-3 plays a critical role in the regulation of the expression of cancer-related genes, including cyclin D1 and Akt (also known as Protein Kinase B; PKB)." (PMID 24303084, 2013). "Numerous studies focused on the molecular mechanisms of galectin-3 involved in cancer cell chemoresistance." (PMID 24303084, 2013). "Here, we report that galectin-3 levels in the sera of patients with metastatic PCa were uniformly higher as compared to the non-cancer patient controls." (PMID 23625538, 2013). "Galectin-3 is a mammalian β-galactoside-binding protein that is expressed by various types of human cells and plays an important role in cancer cell growth, transformation, apoptosis, angiogenesis, adhesion, invasion, and metastasis." (PMID 23401782, 2013). "Our data showed that serum galectin-3 levels peak in the most advanced PCa and are decreased in the non-cancer men." (PMID 23625538, 2013). "Galectin-3 expression is dysregulated in transformed cells, being highly expressed in numerous different types of cancer cells." (PMID 24115933, 2013). "Galectin-3 plays an anti-apoptotic role in many cancer cells and regulates various pathways to activate MDR." (PMID 24303084, 2013). "This is the first study showing that patients with metastatic PCa have higher serum galectin-3 concentrations than non-cancer control patients." (PMID 23625538, 2013). "This is the first report to show serum galectin-3 levels in metastatic PCa and non-cancer control patients." (PMID 23625538, 2013). "Galectin-3 is an important anti-apoptotic effector protein that confers resistance to cancer chemotherapy." (PMID 24303084, 2013). "Cell surface galectin-3 is involved in various cell-cell and cell-matrix interactions and enhances cancer cell adhesion and invasion through basement membrane by interacting with extracellular matrix proteins such as fibronectin, collagen, or laminin." (PMID 23265237, 2012). "Galectin-3 was considered a candidate protein of interest because of its higher expression in spheres compared to adherent cells, its known roles in cancer progression, its expression on the plasma membrane and its ability to be blocked with small molecules." (PMID 23285151, 2012). "Galectin-3 is expressed widely in epithelial and immune cells and its expression is correlated with cancer aggressiveness and metastasis." (PMID 23265237, 2012). "MCP is relatively rich in galactose, and antagonizes a binding protein galectin-3 (Gal-3), which results in suppression of cancer cell aggregation, adhesion, and metastasis." (PMID 21816083, 2011). "High levels of galectin-3 in these subtypes have spurred the use of galectin-3 in imaging of these cancers and as therapeutic target." (PMID 22039439, 2011). "The aim of the study was to quantify galectin-3 and Beclin1 mRNA in human cancer tissue cDNA panels and determine their utility as biomarkers of cancer cell survival." (PMID 22039439, 2011). "Galectin-3 mRNA levels were higher than Beclin1 in all tissue types and over-and under-expression of both galectin-3 and Beclin1 were seen in normal and cancer tissues." (PMID 22039439, 2011). "One study found strongly increased binding of galectin-3 to a haptoglobin like protein on western blots of sera from cancer patients, but only after desialylation." (PMID 22028908, 2011). "Galectin-3 is a 31 kDa carbohydrate-recognition protein, involved in tumorigenesis, cancer cell growth and metastasis and its high expression in several human cancers has been found to correlate with the poor prognosis of metastatic cancers." (PMID 21966428, 2011).